HDAC9 (histone deacetylase 9)
Diseases named in the same sentence as HDAC9 in open-access papers (continued):
Sharing a sentence is not in itself a finding about the gene and the disease.
cancer (continued). "The HDAC9 (histone deacetylase 9) gene is overexpressed in cancer cells and is a member of a family of enzymes responsible for the deacetylation of lysine residues, a key event in the aberrant epigenetic repression in cancer." (PMID 35406435, 2022). "Intriguingly, HDAC1 and 7 are over-expressed in cancer stem cells, whereas, HDAC9 and 10 are both essential for homologous recombination in malignant ovarian tumors." (PMID 36034650, 2022). "Given the important role of HDAC9 particularly in the cardiovascular system and in cancer, further studies aiming to characterize the complexity of this epigenetic regulator are strongly encouraged." (PMID 33513699, 2021). "HDAC9 overexpression is also common in cancer cells, where HDAC9 alters the expression and activity of numerous relevant proteins involved in carcinogenesis." (PMID 34318404, 2021). "Alongside the role played by HDAC9 in regulating fitness, survival and the metabolic reprogramming of cancer cells, recent evidence reports a role of the deacetylase in regulating the tumor microenvironment and anti-tumor immunity." (PMID 33513699, 2021). "The relationships between HDAC9 levels and cancer are various and it can impact different steps of the tumorigenic process." (PMID 33513699, 2021). "In summary, all the reported data on HDAC9 in cancer cells, although obtained in different models and in the presence of different stimuli, point to a pro-oncogenic activity for this deacetylase." (PMID 33513699, 2021). "The following sections describe these newly identified targets and functional partners of HDAC9 based on their physiologic roles and potential contributions to cancer development." (PMID 34318404, 2021). "HCC cells abruptly up-regulate HDAC9 mRNA in response to sulfatide a pro-metastatic sulfated glycolipid, further sustaining a role of HDAC9 in cancer onset and progression." (PMID 33513699, 2021). "Frequently, cancer cells are HDAC9-addicted, thus boosting further efforts in the identification of specific HDAC9 inhibitors." (PMID 33513699, 2021). "HDAC9 is highly expressed in BRM-negative carcinoma cell lines including SW13 and C33A, which are derived from adrenal and cervical carcinomas, respectively." (PMID 34318404, 2021). "Specific knockdown of HDAC9 in BRM-negative carcinoma cells led to an induction of BRM expression and a significant suppression of cell growth." (PMID 34318404, 2021). "Loss-of-function ARID1A mutations sensitized various cancer cells towards inhibition of EZH2, PARP, ATR, HSP90 and HDAC9 (and others)." (PMID 32272809, 2020). "Given that previous work has shown that HDAC9 can down-regulate miR-376a and thereby promote cancer, future studies should identify genes, miRNAs and ncRNAs targeted by HDAC9 in drug-resistant HCC." (PMID 33552961, 2020). "Recent studies have demonstrated both pro-oncogenic and tumor suppressive role for HDAC9 in different cancers." (PMID 31365693, 2019). "The expression of HDAC9 was semiquantitatively assessed by scoring the intensity of the staining and the proportion of positive cancer cells." (PMID 31451695, 2019). "The occurrence of B-NHL in these transgenic mice strongly indicates a link between deregulated HDAC9 expression and lymphoid neoplasia, the first time that overexpression of a histone deacetylase in mice has resulted in a cancer phenotype." (PMID 27799148, 2016). "Using data from The Cancer Genome Atlas we demonstrate that a subset of PDACs exhibits a strong pro-angiogenic signature that includes 37 genes, such as HDAC9, that are overexpressed in PDAC arising in KRC mice, which express mutated Kras and lack RB." (PMID 25762644, 2015). "HDAC9 was also abundant in nuclei of cancer cells, CAFs and CD31-positive vessels in EUS-PDOX tumors and KRC mPDACs." (PMID 25762644, 2015). "We previously found that the transcription factors MEF2D and GATA3, as well as the histone deacetylases HDAC3 and HDAC9, regulate BRM expression in BRM-deficient cancer cell lines." (PMID 24913006, 2014).
cancer (continued). "HDAC8 alters cancer cell proliferation, cell cycle, and differentiation, and HDAC9 could mediate cancer cell proliferation, autophagic flux, and chemoresistance." (PMID 40283998, 2025). "Histone deacetylase 9 (HDAC9) is known to be upregulated in various cancers." (PMID 38920983, 2024). "Identifying the molecular network involving CAGEs and HDAC9 may also be helpful for achieving a better understanding of anti-cancer drug resistance." (PMID 38920983, 2024). "In addition, it is necessary to identify downstream targets of HDAC9 to improve our understanding of CAGE-promoted anti-cancer drug resistance." (PMID 38920983, 2024). "Thus, CAGEs and HDAC9 are likely to promote anti-cancer drug resistance by regulating autophagic flux." (PMID 38920983, 2024). "We also showed that HDAC9 was necessary for anti-cancer drug resistance and autophagic flux." (PMID 38920983, 2024). "It has been reported that HDAC9 is highly expressed in many cancers." (PMID 36227941, 2022). "Because HDAC9 expression is generally correlated with a poor prognosis and reduced survival rates, the detection of HDAC9 in cancer patients may be of prognostic value." (PMID 34318404, 2021). "In the context of cancer progression, this environmental control on HDAC9 levels could provide an important contribution to the adaptation of the cancer cells to a hostile hypoxic environment." (PMID 33513699, 2021). "There are also cancers where HDAC9 expression is dysregulated at post-transcriptional levels." (PMID 33513699, 2021). "Because high levels of HDAC9 are frequently associated with advanced malignancy and poor clinical outcomes, therapeutics that target HDAC9 might be explored for the treatment of one or more types of cancer." (PMID 34318404, 2021). "HDAC9 transcripts were frequently found up-regulated in cancer cells." (PMID 33513699, 2021). "The contributions of HDAC9 to specific types of cancer have been studied worldwide." (PMID 34318404, 2021). "However, the role of class IIa HDACs with weak deacetylation activity, such as HDAC9, in cancer remains elusive." (PMID 33042272, 2020). "The authors suggest that selective HDAC9 inhibitors could help to improve the survival of patients with this type of cancer." (PMID 31451695, 2019). "Several studies have confirmed that HDAC9 is involved in the development of malignant tumors." (PMID 31451695, 2019). "Fewer data have been published on HDAC9 in the context of cancer." (PMID 26930713, 2016). "Moreover, 34/54 (∼63%) PDACs in the TMA exhibited strong HDAC9 immunoreactivity in the cancer cells, and in these tumors, CD31-positive endothelial cells were abundant." (PMID 26586478, 2016). "Just why HDAC9 overexpression appears to selectively occur in BRM-deficient cancer cells is not known." (PMID 25774356, 2014). "Alternatively, as HDAC9 is a class 2 HDAC, its expression is relatively tissue-specific, and because it is highly overexpressed in BRM-deficient cancer cells, it might be a viable target for therapy." (PMID 25774356, 2014). "HDAC9 plays a role in hematopoiesis, and its deregulated expression, along with altered expression of TGF-β2, may be associated with human cancer and Peters' anomaly." (PMID 21518438, 2011). "This review summarizes the most recent discoveries regarding HDAC9 as a crucial regulator of specific physiological systems and, more importantly, highlights the diverse spectrum of HDAC9-mediated posttranslational modifications and their contributions to cancer pathogenesis." (PMID 34318404, 2021). "Besides, silencing of HDAC9 can stop sprouting in vitro and reduce vessel growth in a zebrafish model in vivo via the repression of the miR-17-92 cluster, indicating a possible common therapeutic target for cancer vasculogenesis." (PMID 34603017, 2021). "Moreover, based on our results, it appears likely that targeting HDAC9 might represent a novel therapeutic target to treat endocrine therapy‐resistant cancers." (PMID 31099456, 2019).
cancer (continued). "Further studies on HDAC9 and miR-512 are necessary for a better understanding of CAGE-promoted anti-cancer drug resistance in relation to autophagy." (PMID 38920983, 2024). "High levels of HDAC9 expression in AML, as with other cancers, are significantly correlated with a diminished overall survival." (PMID 34318404, 2021). "HDAC9, as a member of the HDAC IIa family, regulates diverse diseases including neurodegenerative diseases, cancer, and cardiovascular diseases." (PMID 32375326, 2020). "The Cancer Genome Atlas (TCGA) dataset analysis revealed that HDAC4, HDAC7 and HDAC9 as well as HDAC class I members HDAC1 and HDAC2 is significantly correlated with patient survival." (PMID 31635225, 2019). "Accordingly, in addition to the identified placental targets, HDAC9 has been widely studied in the context of cancer and cardiovascular disease but has not been exclusively limited to these disease states." (PMID 41416997, 2025). "The downregulation of HDAC9 also decreased SOX2, a marker of cancer stemness, in AGSR cells." (PMID 38920983, 2024). "HDAC9 has the ability to reduce EGFR expression and hence inhibit the activation of the downstream PI3K/AKT signaling pathway, which leads to the development of cancer." (PMID 36619866, 2022). "Our data indicated that 3′-UTR variations in HDAC9 and EGFR may promote cancer development through posttranscriptional regulation." (PMID 35654793, 2022). "HDAC9 and SIRT7 showed widespread CNV amplification across cancer types." (PMID 34136387, 2021). "Class II HDACs, including HDAC5, HDAC6, and HDAC9, have been reported to catalyze the deacetylation of cytoplasmic, non-histone proteins in cancer cells." (PMID 32977608, 2020). "In patient P4, two of four malignant ascites-emerging clones may be targetable by inhibitors against BRAF (e.g. Vemurafenib), TEP1, ERBB4, PIK3CA, HDAC9, or FYN." (PMID 26811494, 2016). "In the present study, we determined that HDAC9 is strongly expressed in the cancer cells in PDAC tissues with abundant vasculature, raising the possibility that HDAC9 could be a new marker for angiogenesis in PDAC." (PMID 26586478, 2016). "Knockdown of HDAC3 had no impact on HDAC9 expression, but readily induced BRM and caused BRM-dependent growth inhibition, which paralleled our observations in the non-Rhabdoid BRM-deficient cancer cell lines SW13 and C33A." (PMID 24913006, 2014).
tumor (1,616 papers, 2005 to 2026). "HDAC9 deficiency promoted tumor progression by decreasing CD8+ dendritic cell (DC) infiltration in the tumor microenvironment." (PMID 35359455, 2022). "HDAC9 expression in PDAC tissues was found to be negatively associated with tumor size and with T and N stages." (PMID 34318404, 2021). "An intriguing finding is the complete loss of HDAC9 in the hFL-HCC tumour line; the relevance of this to the pathogenic properties of hFL-HCCs is not yet understood." (PMID 26437858, 2015). "At the same time, upregulation of HDAC9 might be the cause of the inherent drug resistance of tumor cells." (PMID 40145017, 2025). "Moreover, over-expression of HDAC9 is frequently associated with tumor progression and poor prognosis." (PMID 31365693, 2019). "HDAC activity is indeed deregulated in pBTs and is involved in tumour formation and growth; for example, HDAC5 and HDAC9 are highly expressed in MB and are associated with poor overall survival." (PMID 41471075, 2025). "It has been suggested that the CBR3-AS1/miR-509-3p/HDAC9 pathway is a valuable target for the therapy of NSCLC since it promotes tumor growth through the development and progression of NSCLC." (PMID 40356687, 2025). "The results showed that CCR7, KMO, IF57, and HDAC9 were highly expressed in HNSCC tumor tissues, while ZNF439 was highly expressed in normal tissues." (PMID 40145017, 2025). "The analysis of showed that PHF19, AURKA, CHAF1B and AURKB were up-regulated in the tumor group, NAP1L2, TONSL, SATB2 and HDAC9 were down-regulated in the tumor group." (PMID 38212708, 2024). "In our comprehensive analysis of HDACs in DLBCL patients using public databases, we found that the expression levels of HDAC1, HDAC2, HDAC3, HDAC6, HDAC7, HDAC8, and HDAC9 were higher in tumor tissues compared to normal control for the first time." (PMID 38168914, 2024). "Among them, PHF19, AURKA, CHAF1B and AURKB were up-regulated in the tumor group, NAP1L2, TONSL, SATB2 and HDAC9 were down-regulated in the tumor group." (PMID 38212708, 2024). "Another member of the class IIa HDACs, HDAC9, interacted with transcriptional suppressors and oncogenic proteins, modulating anti-tumor immunity by controlling CD8+ dendritic cells and T cell infiltration." (PMID 38702756, 2024). "The downregulation of HDAC9 decreased the autophagic flux, invasion, migration, and tumor spheroid formation potential in AGSR cells." (PMID 38920983, 2024). "HDAC9 has been reported to have oncogenic effects in OSCC by targeting proapoptotic genes to promote tumor growth." (PMID 39282225, 2023). "Compared with normal bladder tissues, HDAC9 was found to be lower in tumor tissues according to TCGA and HPA data." (PMID 35239708, 2022). "The exogenous expression of miR-383-5p inhibited HDAC9 expression in tumor tissues from GC-bearing nude mice." (PMID 36313570, 2022). "The level of HDAC9 was higher in RB samples, and this upregulation was correlated with tumor size, regional lymph node metastasis, and poor tumor differentiation." (PMID 36619866, 2022). "Compared with wild-type mice, the tumor-infiltrating DCs of Hdac9−/− mice presented decreased cross-presentation of tumor antigens and cross-priming of CD8+ T cells." (PMID 35514980, 2022). "For example, the expression of HDAC9 was shown to be highly upregulated in GBM, thereby causing an increased tumor proliferation by activating the transcription coactivator with PDZ-binding motif (TAZ), an important downstream component in the Hippo pathway." (PMID 36425564, 2022). "The restoration of HDAC9 expression led to a decrease in the tumor-suppressor effects of miR-936, and increased the oncogenicity of RB cells." (PMID 36619866, 2022). "The pro-tumor effects of HDAC9 have been demonstrated in breast cancer, oral squamous cell carcinoma, and retinoblastoma." (PMID 36313570, 2022).
tumor (continued). "In comparison, among 16 downregulated genes relative to IQGAP1 under-expression, FAM65B (RIPOR2), PI15, and HDAC9 are downregulated in either iCluster 1, iCluster 2, or both in comparison to the matched non-tumor tissues." (PMID 33498739, 2021). "HDAC9 is overexpressed in tumor tissue in about 30 % of LMS patients, and HDAC9 levels are inversely correlated with the overall LMS survival rate." (PMID 34318404, 2021). "High levels of HDAC9 expression in primary tumor tissues from GC patients correlated with a lower survival rate." (PMID 34318404, 2021). "Hdac9 is highly expressed in tumor endothelial cells following the engagement of the Stat3 signaling pathway by the neoplastic cells." (PMID 33513699, 2021). "Concerning the clinicopathological characteristics of LADC, PD-1 SNP, ANGPT1 SNP and HDAC9 SNP had been proven to influence the tumor progression significantly." (PMID 33799753, 2021). "OSCC patients with high levels of HDAC9 in their tumor tissue experienced significantly shorter periods of overall survival than patients whose tumor tissues had comparatively lower levels." (PMID 34318404, 2021). "In vitro and in vivo experiments have both suggested a pro-oncogenic role for HDAC9 in GC, as HDAC9 knockdown resulted in reduced GC tumor growth and the induction of GC cell apoptosis and proliferation." (PMID 34318404, 2021). "The level of expression of histone deacetylases has an influence on tumor progression; for instance, the overexpression of HDAC9 stimulates the development of OSCC by alterations of the cell cycle, cell proliferation, and apoptosis." (PMID 31712935, 2020). "When discriminating each tumor subtype, the SE components were the ones with significantly lower expression of HDACs, except for HDAC9." (PMID 33050470, 2020). "In conclusion, we showed for the first time that miR-383-5p was decreased in GC tissues and cell lines and served as a tumor suppressor by inhibiting HDAC9 expression to prevent gastric carcinogenesis." (PMID 31365693, 2019). "Previous studies have shown that several miRNAs target HDAC9 to exert their tumor repressive effect." (PMID 31365693, 2019). "In our study, we showed that miR-383-5p functioned as a tumor suppressor in GC by inhibiting HDAC9 expression." (PMID 31365693, 2019). "Data analysis revealed high immunoreactivity in 93.3% of tumor tissues (14/15, IHC score ≥ 8) but low expression of HDAC9 in 73.3% of adjacent normal tissues (11/15, IHC score ≤ 4), indicating an increase in HDAC9 expression in cancerous tissues." (PMID 31451695, 2019). "Among HDACs 1-10, class I HDACs (HDAC1, HDAC2, HDAC3, and HDAC8) and HDAC9 were more highly expressed in CCA tissues compared with paired non-tumor tissues (P<0.05)." (PMID 27705912, 2016). "HDAC9, a member of HDAC family, is linked to tumor development and regulates cell cycle and apoptosis." (PMID 27821810, 2016). "We generated three independent transgenic lines (designated as 1468, 1469 and 1839) and monitored a total of 124 mice (78 Eμ-HDAC9 and 46 wild type) for tumor formation and overall survival." (PMID 27799148, 2016). "The expression of Ki67 in the tumor tissues formed by the HDAC9-knockdown U87 cells was decreased compared with the shGFP cells." (PMID 25760078, 2015). "The expression of these proteins in HDAC9-knockdown cells and in the tumor tissues formed by the HDAC9-knockdown U87 cells was all markedly reduced compared with their controls." (PMID 25760078, 2015). "All these results suggested that the HDAC9-promoted proliferation and tumor formation of GBM cells were possibly mediated by potentiating the EGFR signaling pathway." (PMID 25760078, 2015). "Tumor xenograft experiments in SCID mice indicated that HDAC9 significantly promoted tumor growth in vivo." (PMID 25760078, 2015). "The results suggested that HDAC9 most likely enhanced the tumor progression of GBM cells by promoting cell proliferation." (PMID 25760078, 2015).